TNF (tumor necrosis factor)
Diseases named in the same sentence as TNF in open-access papers (continued):
Sharing a sentence is not in itself a finding about the gene and the disease.
brucellosis (continued). "In addition, the results of Demirdag and colleagues showed that serum level of TNF- α was high in patients than in controls and reported that this cytokines involved in the pathophysiology of brucellosis." (PMID 31818255, 2019). "In addition to the frequency of Th1 cells, the mean serum levels of IFN-γ and TNF-α were significantly higher in the brucellosis patients when compared with the healthy subjects (p < 0.05)." (PMID 31686983, 2019). "As an intracellular bacterium, Brucella may have similar biological indicators, yet we found a significant difference in IFN-γ/TNF-α ratios between the brucellosis patients and healthy subjects." (PMID 31686983, 2019). "The IFN-γ/TNF-α ratio may be a feasible parameter for assessing clinical severity, yet further longitudinal studies of the immunization and inflammatory reaction of brucellosis are needed in larger patient populations." (PMID 31686983, 2019). "However, 3-MA treatment restored TNF-α production by M1 macrophages and IL-10 secretion by M2 macrophages in brucellosis patients." (PMID 28659924, 2017). "Additionally, the production of IL-1β, IL-6, IL-10, and TNF-α from monocytes in patients with brucellosis was suppressed through the LC3-dependent autophagy pathway during Brucella infection." (PMID 28659924, 2017). "In addition to this, Brucella change the cytokine level of IFN-γ, TNF-α, IL-10 and TGFβ1 in the early stages of brucellosis in a prpA dependent manner." (PMID 27014640, 2016). "Additionally, IL-12, IFN-γ, and TNF-α are key cytokines in brucellosis, initiating innate and adaptive immune response and giving directions to immune-associated cells." (PMID 27014640, 2016). "TNF-α participates in DC maturation and critical to control murine brucellosis." (PMID 22927979, 2012). "A fraction of CD8+ T cells show a CD8+ Tmem phenotype of LFA-1hi, CD127hi, KLRG-1lo during the course of chronic brucellosis, while the CD8+ T cell pool as a whole had a very weak polyfunctional cytokine response with diminished co-expression of IFN-γ with TNFα and/or IL-2, a hallmark of exhaustion." (PMID 22558103, 2012). "Other pro-inflammatory cytokines essential in controlling brucellosis include IL-6, IFN-γ, and TNF-α." (PMID 40589729, 2025). "Significantly higher levels of TNF-α, IFN-α, and IL-6 also distinguished SLAMFhi from SLAMFlo brucellosis patients." (PMID 40231463, 2025). "We investigated changes in the levels of six cytokines (IL-4, IL-6, IL-10, IL-17, TNF-α, INF-γ) and related clinical biochemical markers in patients with acute and chronic brucellosis in Xinjiang, China." (PMID 32381058, 2020). "In summary, brucellosis patients have a higher frequency of circulating Th1 cells and higher levels of Th1 cytokines, including IFN-γ and TNF-α." (PMID 31686983, 2019). "are able to survive and replicate within macrophages, and effective control of brucellosis requires a potent Th1 response to activate cellular mediated immunity which is driven by the production of IFN-γ, IL-2, and TNF-α." (PMID 24040434, 2013). "To further investigate the cytokine production of CD8+ T cells during chronic brucellosis, we examined the expression of IFN-γ, TNF-α, and IL-2 independently of one another." (PMID 22558103, 2012). "As the major contributor of potential inflammatory storm, many inflammatory response genes (e.g., ITGB2, OSM, FPR1, CEBPB, NINJ1) and canonical pro‐inflammatory cytokines (e.g., CXCL8, CCL3, CCL4, TNF, IL1B, S100A12) were expressed at higher levels in brucellosis patients than in healthy donors." (PMID 39135683, 2024). "Further analysis found that granzyme/perforin, TNF, XAF1, and FAS apoptosis pathways might contribute to apoptosis of NK cells in patients with brucellosis, potentially exerting a direct inhibitory effect on NK cell‐mediated responses." (PMID 39135683, 2024).
brucellosis (continued). "Procarta cytokine analysis from the plasma of these individuals, supported the finding that brucellosis patients, especially for acute patients, had a higher level of multiple pro‐inflammatory cytokines, such as CXCL8/IL8, CCL3/MIP‐α, CCL4/MIP‐β, TNF/TNF‐α, IL1B/IL1‐β." (PMID 39135683, 2024). "The upregulated genes in granzyme/perforin, TNF, XAF1 and FAS apoptosis pathways may result in elevated apoptosis of CD8+ T cells in brucellosis patients and thus directly inhibit CD8+ T‐cell‐mediated responses." (PMID 39135683, 2024). "In the acute phase of brucellosis, infected patients exhibit higher levels of cytokines, such as TNF-α, IL-6 or IFN-γ, and IL-10, compared to Brucella-negative individuals." (PMID 38139181, 2023). "In vivo, IL-6, TNF-α, and CD80/CD86 are required for activation of the interferon gamma-producing CD4+ Th1 and CD8+ cytotoxic T cells, a protective response induced by the host against brucellosis." (PMID 34992597, 2021). "In vivo, IL-6, TNF-α, and CD80/CD86 are required in the activation of the interferon gamma-producing T CD4+ helper type 1 (Th1) and T CD8+ cytotoxic, a protective response induced by the host against brucellosis." (PMID 32765455, 2020). "In the early stages of brucellosis, Brucella change the cytokine level of IFN-γ, TNF-α, and IL-10." (PMID 29435171, 2018). "Positive controls were noted to have significantly increased expression of genes associated with the inflammatory response, including CCL5 (chemokine ligand 5), MEFV (Mediterranean Fever, codes for pyrin), SLC11A (solute carrier family 11 member 2), and TNF (tumor necrosis factor) (P < .0001)." (PMID 28943993, 2017). "Proinflammatory cytokines, particularly TNF-α, increase during acute Gram negative infections but not at the onset of brucellosis." (PMID 19529776, 2009). "In addition, the authors reported that TLR6 (but not TLR2) is required for the in vivo control of the bacteria in the murine model of brucellosis, and that murine DCs lacking TLR2 or TLR6 are unable to produce of TNF-α or IL-12." (PMID 23805193, 2013). "It is also significant that the ability of macrophages to control intracellular B. abortus is affected by IL-10 only at very high concentrations, and that IL-6 and TNF-α have no major effect, in contrast to INF-γ which is the key cytokine in the control of brucellosis." (PMID 17637846, 2007).
cholangiocarcinoma (34 papers, 2010 to 2024). A carcinoma that arises from the intrahepatic biliary tree (intrahepatic cholangiocarcinoma) or from the junction, or adjacent to the junction, of the right and left hepatic ducts (hilar cholangiocarcinoma). "Some scholars have found that in cholangiocarcinoma xenograft tumors, stigmasterol can significantly reduce the expression of tumor necrosis factor-alpha (TNF-α) and inhibit further tumor angiogenesis after intervention, thus inhibiting tumor progression." (PMID 38324023, 2024). "In conclusion, our findings demonstrate that WZ26, as a curcumin optimized analog, can inhibit the migration, invasion, and EMT of cholangiocarcinoma cells induced by TNF-α." (PMID 36647192, 2023). "The proinflammatory cytokine TNF‐a triggers endothelial mesenchymal transition in cholangiocarcinoma, promoting a tendency toward metastasis." (PMID 35898846, 2023). "In vitro and in vivo studies of human cholangiocarcinoma showed that lovastatin overcomes gefitinib resistance by upregulating tumor necrosis factor-α (TNF-α)." (PMID 34065757, 2021). "In vivo studies have shown that TNF‐a can induce the overexpression of MMP9 in cholangiocarcinoma cell lines." (PMID 32735065, 2020). "It has been reported that mice treated with stigmasterol inhibits cholangiocarcinoma growth through suppressing tumor angiogenesis by downregulation of tumor necrosis factor-alpha." (PMID 31010220, 2019). "The induction of MMP-9 by PGE2 in TNF-α treated cholangiocarcinoma cells has been reported to occur through the activation of EP2/4 receptors." (PMID 25595899, 2015). "This suggests that although there are different gene statuses in these two cholangiocarcinoma cell lines, gefitinib can potentiate lovastatin-induced antiproliferation through enhancing TNF-α expression." (PMID 26160843, 2015). "In this study, lovastatin induced apoptosis or cell cycle arrest through TNF-α pathway in two gefitinib-resistant human cholangiocarcinoma cells." (PMID 26160843, 2015). "In gastric and cholangiocarcinoma cell lines, proinflammatory cytokines including IL-1β, IL-6, and TNF-α have all been reported to induce Cdx2 gene expression." (PMID 26460825, 2015). "Activation of ERK1/2 and p38, followed by the NF-κB axis, which is stimulated by tumor necrosis factor-α (TNF-α), also occurs in cholangiocarcinoma." (PMID 24004445, 2013). "In addition, stigmasterol markedly disrupted angiogenesis in human cholangiocarcinoma by tumor necrosis factor-α (TNF-α) and vascular endothelial growth factor receptor-2 (VEGFR-2) signaling down-regulation." (PMID 36290632, 2022). "In another study, the decreased number of TNF-α producing DCs in cholangiocarcinoma patients could affect DC-mediated immunity." (PMID 33922362, 2021). "Interestingly, they found that macrophages positive for TNF-α were commonly observed at the invasive front of cholangiocarcinoma compared with the central part of CC." (PMID 24993803, 2014). "In addition, TFK-1 cells (human cholangiocarcinoma cell line) were stimulated with lipopolysaccharide (LPS) or tumor necrosis factor (TNF)-α." (PMID 25187820, 2014). "Furthermore, TNF-α stimulation was shown to induce over-expression of fascin that in turn up-regulate MMP-9 expression in cholangiocarcinoma." (PMID 22076152, 2011). "The increased levels of CD40 seen in diseased tissue and cholangiocarcinoma could be explained by high local levels of proinflammatory cytokines such as TNFα and IFN-γ at sites of persistent chronic inflammation." (PMID 21103345, 2010). "In an in vivo xenograft model, lupeol suppressed growth of cholangiocarcinoma (CCA) tumor, and the inhibitory mechanism of lupeol was suggested via the suppression of TNF-α and downstream effectors of VEGFR-2 signaling." (PMID 35267408, 2022). "It has been previously reported that tumor necrosis factor α-induced MMP-9 production in cholangiocarcinoma (CC) cells is concurrent with enhanced fascin-1 expression." (PMID 24993803, 2014).
cholangiocarcinoma (continued). "Several studies have shown increased expression of RAB7A in cholangiocarcinoma cells following the induction of epithelial–mesenchymal transition (EMT) and invasion by tumour necrosis factor-α (TNF-α) stimulation." (PMID 36261459, 2022). "In cholangiocarcinoma, CXCL12 is positively modulated by angiotensin II and negatively by TGF-β, while CXCR4 expression is promoted by TNF-a-secreting TAMs." (PMID 33922362, 2021). "With regard to stigmasterol, it’s a major phytosterol in herbal plants, which can downregulate levels of inflammatory cytokines involving TNF-α,repress VEGF signaling, produce anti-angiogenic effects, thus inhibit cholangiocarcinoma growth in mice." (PMID 33478536, 2021). "In cholangiocarcinoma (bile duct cancer), the presence of TNF-α and IFN-γ, due to early inflammatory, stimulates MSCs to secrete TNF-α, CCL5 and IL-6, to express indoleamine 2,3-dioxygenase, to activate NF-κB, and to increase their migratory abilities." (PMID 32630699, 2020). "Techasen et alhave demonstrated that tumor necrosis factor-α (TNF-α), an inflammatory cytokine largely secreted from tumor stromal cells, stimulates EMT activation and significantly upregulated Snail expression in cholangiocarcinoma tissues." (PMID 36467998, 2022).
cutaneous leishmaniasis (34 papers, 2006 to 2025). Leishmaniasis affecting the skin. "From the results of DisGeNET, the hub genes IL10, IL6, CXCL8, CSF2, IFNG, IL1B, and TNF were causing Visceral Leishmaniasis; IL10, IL4, CXCL8, IFNG, IL1B and TNF found to cause Cutaneous Leishmaniasis and Urban Cutaneous Leishmaniasis." (PMID 36989283, 2023). "The tissue repair process is critically important for rapid cure of cutaneous leishmaniasis, as demonstrated in L. (L. ) major murine cutaneous leishmaniasis, and is associated to reduced IL-10 and increased TNF-α, IFN-γ and the TGF-β pathway." (PMID 27579922, 2016). "High levels of proinflammatory cytokines such as IFN-γ and TNF are associated with tissue lesions in cutaneous leishmaniasis (CL)." (PMID 23209879, 2012). "Cutaneous leishmaniasis (CL) is an infectious disease characterized by severe local inflammatory response, predominantly mediated by cytokines such as IL-1β and TNF, and cytotoxicity, contributing to tissue damage and lesion development." (PMID 41200163, 2025). "During cutaneous leishmaniasis (CL), intermediate monocyte are reported to be a source of inflammatory cytokines IL-1β and TNF, and they express CCR2 attracting them to sites of inflammatory pathology." (PMID 38669292, 2024). "According to the results, TNF-α can impact melatonin production in individuals with American cutaneous leishmaniasis." (PMID 39199338, 2024). "Previously, we observed higher levels of IP-10 and MIG, IFN-γ, and TNF in active and self-healed cutaneous leishmaniasis regulating parasite growth control." (PMID 34178725, 2021). "Specifically, in cutaneous leishmaniasis caused by L. braziliensis miR-361-3p, a regulator of GZMB and tumor necrosis factor (TNF) was down-regulated and related to treatment failure." (PMID 34178725, 2021). "Collectively, our studies revealed that up-regulated TLR2/4 expression and TNF production by intermediate/inflammatory subsets of monocytes from patients correlates with detrimental outcome of cutaneous leishmaniasis." (PMID 31119102, 2019). "The generation of reactive oxygen species (ROS), especially superoxide, and tumor necrosis factor-alpha (TNF-α) had both been shown to play an important role in the control of cutaneous leishmaniasis." (PMID 28690662, 2017). "Our results describing a fatal course of L. major infection in TNF-/- contrast with two other studies published in experimental cutaneous leishmaniasis, which either used anti-TNF antibodies in C3H/HeN mice or a Tnf-/- strain on a different mouse background." (PMID 26834705, 2015). "Leishmania killing is associated to macrophage activation by IFN-γ and TNF-α and the production of nitric oxide, whereas TGF-β is an immunosupressor cytokine known to exacerbate visceral and cutaneous leishmaniasis." (PMID 22616018, 2012). "Recently, we demonstrated that the recombinant S. mansoni antigens Sm29 SmTSP-2, and also PIII down-modulated the production of IFN-γ and TNF in a group of cutaneous leishmaniasis (CL) patients." (PMID 23209879, 2012). "In immunization of mice against L. amazonensis, ScLL induced increased levels of IgG2a and overexpression of IL-12 and TNF-α mRNAs, leading to a Th1-biased immune response that supported the protective function of this lectin against cutaneous leishmaniasis." (PMID 23107170, 2012). "Levels of TNF-α by PBMC from cutaneous leishmaniasis patients were significantly higher than disseminated leishmaniasis patients only when stimulated by genotyped cutaneous leishmaniasis antigens." (PMID 16638143, 2006). "However, in diffuse cutaneous leishmaniasis, there was a reduction of NK cells and low levels of proinflammatory immune mediators, such as IFN-γ and TNF-α, when compared to localized cutaneous leishmaniasis." (PMID 39963187, 2025). "The effect LPG has on both IL12 and TNF may contribute to the overall skewing of L. major towards a predominant Th1 response during cutaneous leishmaniasis." (PMID 26630499, 2015).
cutaneous leishmaniasis (continued). "Previous studies revealed that protection against L. major infection in mice and healing of cutaneous leishmaniasis in humans correlates with the priming of multifunctional Th1 CD4+ T cells that simultaneously secrete high amounts of IFN-γ, IL-2, and TNF-α." (PMID 23840706, 2013). "In murine cutaneous leishmaniasis, the degree of protection in vaccinated mice was predicted by the frequency of CD4+ T cells simultaneously producing interferon-γ (IFN-γ), interleukin (IL)-2 and tumour necrosis factor (TNF, formerly TNF-α)." (PMID 23150744, 2012). "Resistance to American cutaneous leishmaniasis is related to the emergence of responses with the participation of CD4+ T cells with a Th1 profile, with the production of pro-inflammatory cytokines such as IL-1, IL-2, IL-12, IFN-γ, and TNF-α, which lead to macrophage activation and parasite death." (PMID 39199338, 2024).